CRP (C-reactive protein)
Diseases named in the same sentence as CRP in open-access papers (continued):
Sharing a sentence is not in itself a finding about the gene and the disease.
COVID-19 (continued). "We included the acute inflammation marker C-Reactive Protein (CRP), leukocyte cell count, and the chronic inflammation biomarker suPAR to explore their predictive value for impaired DLCO among patients with COVID-19 4–5 months post-discharge." (PMID 40095788, 2025). "CRP, albumin, and RDW have also been shown to be deranged and predictive of outcomes in severely ill COVID-19 patients." (PMID 40431641, 2025). "In the context of COVID-19, a cytokine storm—characterized by elevated interleukin-6 (IL-6), tumor necrosis factor-alpha (TNF-α), and C-reactive protein (CRP)—has been proposed as a contributing factor to dyslipidemia." (PMID 40565828, 2025). "We determined that inflammation (CRP, IL-6, fibrinogen, LDH, ferritin) and coagulation (D-dimer, PT) parameters and liver enzymes (AST, ALT, GGT) were preferentially increased in male COVID-19 patients." (PMID 40868247, 2025). "Other acute-phase proteins, including C-reactive protein (CRP) and lipopolysaccharide-binding protein (LBP), were also significantly elevated in PLWH with COVID-19 compared with HCs." (PMID 40568587, 2025). "In an analysis of 697 COVID-19 patients, high values of NLR, D-dimer, procalcitonin, IL-6, and CRP were predictive of mortality, with a proposed NLR cut-off of 9.9." (PMID 40869381, 2025). "In the present study, we investigated the presence of autoantibodies as well as inflammatory markers (C-reactive protein - CRP), in patients hospitalized due to severe COVID-19." (PMID 41259457, 2025). "Our study reveals persistent inflammation following COVID-19 with serum trajectories of novel markers (HBP and SAA), demonstrating dynamics similar to traditional markers (CRP and IL-6)." (PMID 40621180, 2025). "Trehala manna, when used as an adjunct to standard care, was related to a significant reduction in inflammatory biomarkers (CRP level and ESR) and some clinical symptoms (fever and cough) in patients with mild-to-moderate COVID-19." (PMID 40980426, 2025). "Biomarkers such as C-reactive protein (CRP), interleukin-6 (IL-6), and lactate dehydrogenase (LDH) were identified as predictors of COVID-19 severity." (PMID 40385745, 2025). "The levels of inflammatory biomarkers such as CRP (p < 0.0001), PCT (p < 0.0001), D-dimer (p = 0.0214), and IL-6 (p < 0.0001) were significantly higher in patients who died of COVID-19 compared to the recovered patients." (PMID 40241896, 2025). "The literature confirms CTSS correlation with CRP, LDH, and D-dimer levels, supporting their usefulness as markers of COVID-19 severity." (PMID 40648797, 2025). "The decrease in lymphocyte count, similar CRP, ferritin, and organ damage markers such as LDH in patients with COVID-19 is a biomarker of disease severity." (PMID 40364254, 2025). "Patients with COVID-19 exhibit cytokine storm and abnormally high levels of inflammatory mediators, including IL-6, tumor necrosis factor-alpha (TNF-a), and C-reactive protein (CRP)." (PMID 41002604, 2025). "In these studies, patients with MIS-C had higher CRP, D-dimer, and ANC as well as lower ALC and platelets compared to Kawasaki disease and COVID-19." (PMID 41341432, 2025). "In conclusion, our findings demonstrate that conventional inflammatory biomarkers such as CRP, PCT, and ferritin reflect distinct yet overlapping aspects of the cytokine, chemokine, and growth factor network in severe COVID-19." (PMID 41373577, 2025). "Across a total of 17 studies, 7 factors including age, D-dimer, C-reactive protein, sequential organ failure assessment (SOFA) score, body temperature, albumin, and diabetes have the highest consistency as predictors of COVID-19 severity." (PMID 40218195, 2025). "Significant findings in patients with a COVID-19 history include higher PMN percentages, CRP levels, and ALT levels in deceased patients." (PMID 40315194, 2025).
COVID-19 (continued). "The elevated CRP, procalcitonin, NLR, and SII levels in the COVID-19–fungal group align with existing evidence that secondary fungal infections elicit a pronounced immune response." (PMID 40299432, 2025). "In this study, we aimed to evaluate the predictive performance of two widely used prognostic and organ dysfunction scores in critically ill COVID-19 patients admitted to the ICU, as well as the added prognostic value of lactate, CRP, PCT, and LDH." (PMID 40868809, 2025). "For instance, in the COVID-19-NY-SBU dataset, more than half of the patients lack complete data for age, BMI, diabetes, D-dimer, and C-reactive protein (639 out of 1384 patients)." (PMID 40218195, 2025). "Intergroup correlational patterns were analyzed for LVD, ALC, and CRP—the most influential predictors for differentiating LBBB and RBBB in the context of COVID-19." (PMID 40217761, 2025). "Neutrophil count, monocyte count, NLR, MLR, SII, CRP, CK-MB, GLU and IL-6 levels were positively correlated with COVID-19 and PD." (PMID 40292283, 2025). "A prior investigation showed a significant correlation between elevated inflammatory markers, particularly CRP, and lower plasma RBP4 levels in critically ill COVID-19 patients." (PMID 40881125, 2025). "Severe COVID-19 frequently progresses to ARDS, characterized by severe alveolar edema, diffuse inflammation, and elevated markers such as CRP and erythrocyte sedimentation rate." (PMID 41158128, 2025). "A dual-mode Cu-MOF-based aptasensor targeting C-reactive protein (CRP), a biomarker elevated in bacterial and viral infections (including COVID-19), combined fluorescence and colorimetric readouts." (PMID 40871944, 2025). "Numerous laboratory markers, including neutrophils, lymphocytes, CRP, procalcitonin (PCT), and IL‐6, have been reported to be related to the morbidity and mortality of COVID-19." (PMID 41309368, 2025). "Our findings highlight the critical role of various laboratory biomarkers, including hematological indices such as Neutrophil count and NLR as well as inflammation biomarkers like CRP and serum IL-10, in monitoring the severity of ARDS in COVID-19 patients." (PMID 40761632, 2025). "The median concentrations of CRP (P≤0.0001) and LDH (P≤0.0001), and the median leucocyte count (P=0.0066) were significantly higher in the COVID-19 ICU cohort than in the survivors of severe COVID-19 (2.5-yr follow-up cohort)." (PMID 40529720, 2025). "Altered levels of inflammatory markers, such as C-reactive protein (CRP), ferritin, fibrinogen, and the neutrophil-to-lymphocyte ratio (NLR), are frequently observed in hospitalized COVID-19 patients." (PMID 41574058, 2025). "Our analysis revealed significantly higher serum levels of IL-6, CRP, SAA, and PCT in severe COVID-19 patients compared to mild cases, indicating a strong association with disease severity." (PMID 40046064, 2025). "Dysbiosis correlates with elevated inflammatorymarkers, such as CRP and PCT, contributing to severe complications.Studies show that COVID-19 patients have reduced beneficial bacteria,such as and Bifidobacterium spp., alongside increased opportunisticpathogens." (PMID 40471123, 2025). "Older age, elevated levels of CRP, hospitalization in ICU, and PE present independent predictors for impaired outcomes in COVID-19 patients." (PMID 40647684, 2025). "The cluster analysis was carried out using the following factors: SpO2 as an indicator of lung damage, CRP as a marker of inflammation intensity, and AST as another indicator of degree of systemic inflammation in COVID-19." (PMID 40472051, 2025). "Increased C-reactive protein (CRP), alanine aminotransferase (ALT), and aspartate aminotransferase (AST), indicating liver injury, were present on admission in all PLWH/COVID-19." (PMID 41516165, 2025). "Hematological indices (neutrophil count and NLR), CRP, and serum IL-10 hold promise in monitoring ARDS severity in COVID-19 patients." (PMID 40761632, 2025).
COVID-19 (continued). "For example, c-reactive protein (CRP) was considered as a biomarker of sepsis and COVID-19 disease progression." (PMID 40171199, 2025). "HEP6 and HEP7 cells had similar profiles to those in the HEP2 subset but with high expression of acute phase proteins in HEP7 (e.g., CRP, C3, C4a, SAA1, and FTH1; a COVID-19 specific cluster; below) or apoptosis and cellular senescence pathways in HEP6." (PMID 40087773, 2025). "In total, 5 studies reported CRP levels, allowing for the assessment of the biological effect of TNF-α inhibitors in COVID-19." (PMID 40481519, 2025). "A CRP increase after tocilizumab treatment was also predictive of mortality, while we did not observe increased CRP levels in patients with microbiological evidence of bacterial superinfection, meaning rising CRP levels may be rather reflecting progression of COVID-19 in this situation." (PMID 39210228, 2025). "Among hematological parameters, RDW-SD, ALC, ANC, CRP, and ESR emerged as significant separators between LBBB and RBBB individuals with COVID-19." (PMID 40217761, 2025). "Older age, elevated CRP level, and hospitalization in ICU present independent predictors for lethal outcomes in COVID-19 patients with PE." (PMID 40647684, 2025). "Classical inflammatory biomarkers, C-reactive protein (CRP), albumin, and red blood cell distribution width (RDW) have previously been reported to be prognostic in hospitalized COVID-19 patients." (PMID 40431641, 2025). "Other biomarkers, including C-reactive protein (CRP) and procalcitonin (PCT), indicate systemic inflammation and bacterial co-infection, often increasing with COVID-19 severity." (PMID 41012595, 2025). "However, the nonsignificant findings may be attributed to the fact that endometriosis is not typically associated with a significant increase in CRP levels compared to other conditions, such as diabetes, COVID-19, or CVD." (PMID 40224541, 2025). "Among these markers, we identified age, cough, sore throat, CRP, WBC, LY, EO as key variables for constructing a predictive model of COVID-19 disease severity." (PMID 40861215, 2025). "On the other hand, the CRP, Pro BNP, NLR, ADMA, and HSP-90 values were significantly higher in severe COVID-19 patients (p < 0.05)." (PMID 39064471, 2024). "The current study focuses on IL-6 and CRP as potential biomarkers for PCC, as IL-6 is centrally involved in COVID-19 pathology as a pro-inflammatory marker and CRP is a sensitive marker of inflammation (Luan, Yin & Yao, 2021)." (PMID 39056056, 2024). "In COVID-19 patients with ARDS, sNOX2-dp, LPS, zonulin, D-dimer, and hs-CRP were significantly higher compared to COVID-19 patients without ARDS." (PMID 39456513, 2024). "In this sense, a systematic study showed that treatment with MT in a dosage of 5–25 mg/day favored a decrease in the inflammatory markers including IL-6, CRP, and TNF-α in the plasma of COVID-19 patients." (PMID 38674128, 2024). "In the present study, COVID-19 patients showed an increased inflammatory status, as documented in particular by the high serum levels of GDF-15, PIVKA-II, as well as CRP." (PMID 38700782, 2024). "Elevated levels of urea, creatinine, CRP, ferritin, procalcitonin, LDH, and D-dimer are common in AKI and COVID-19 patients." (PMID 39006555, 2024). "In contrast to the control group, the COVID-19 T2DM groups exhibited a significant increase in PAR-1, NT-proBNP, HbA1c, IL-6, D-dimer, TNF-α, CRP, and homocysteine." (PMID 38675414, 2024). "Therefore, while procalcitonin and CRP can complement clinical assessments for initiating or discontinuing antibiotic treatment, further evidence is essential to substantiate their role in distinguishing bacterial co-infection in hospitalized patients with COVID-19." (PMID 38543674, 2024). "All hematological inflammatory markers, including CRP (57.1%), ESR (40.7%), fibrinogen (54.5%), D-dimer (68.8%), PCT (66.7%), and IL-6 (60.7%), were elevated in approximately half of the patients in the COVID-19-related encephalitis group." (PMID 38772979, 2024).
COVID-19 (continued). "The correlation between mortalin level and the level of the laboratory markers of inflammation and tissue damage (e.g., CRP, LDH) observed in COVID-19 patients suggests that mortalin is released from dying or damaged cells." (PMID 38715618, 2024). "This study aimed to assess and compare procalcitonin (PCT) and C-reactive protein (CRP) levels between COVID-19 and non-COVID-19 sepsis patients." (PMID 38172766, 2024). "It has been shown that some of the markers of COVID-19 deterioration and the development of acute respiratory distress syndrome include elevated LDH, CRP, IL-6, D-dimer levels, lymphocytes, platelets, renal function, and also high-sensitive troponin." (PMID 39768950, 2024). "The biomarker with the best discrimination capacity for severe COVID-19 was IL6, with an AUROC of 0.79 (95%CI: 0.66 to 0.93), closely followed by IP10 and CRP (AUROCs of 0.78, 95% CI 0.68 to 0.89; and 0.78, 95% CI 0.67 to 0.89)." (PMID 39664394, 2024). "Furthermore, current studies regarding the predictive performance of CRP and PCT were focused on short-term prognosis of COVID-19 infection, whereas the association between inflammatory biomarkers with long-term prognosis in diabetic patients with COVID-19, especially with ADC remains uncertain." (PMID 38455656, 2024). "The results of univariate analysis showed that WBC, CRP, D-dimer, BUN, SCR, cardiovascular disease, and cerebrovascular disease, coinfection, sepsis, initial COVID-19 stage and antiviral treatment were positively correlated with the risk of adverse outcomes." (PMID 39612427, 2024). "We found that NEWS2, PSI, CURB-65, CRP, NLR, CAR, and LCR were independent predictors of 28-day mortality in COVID-19 patients." (PMID 38671532, 2024). "A significantly increased ALT level as well as higher inflammatory indices (CRP, LDH, ferritin, and procalcitonin) and IL-6 levels were detected in COVID-19 patients compared to controls, with the highest values in severe and critically ill patients." (PMID 38703289, 2024). "This study provided the first evidence that PAR-1 levels rise in COVID-19-affected T2DM patients, and it identified a positive correlation between serum BMI, PAR-1 levels, CRP, HbA1c, D-dimer, homocysteine, NT-proBNP, and other inflammatory mediators." (PMID 38675414, 2024). "However, in the multivariate analysis, CRP was not independently associated with TB/COVID-19 comorbidity, suggesting that other factors may act as confounding variables." (PMID 39536219, 2024). "Nonetheless, the significance of other blood markers, like C-reactive protein (CRP) and interleukin (IL)-6, in forecasting COVID-19 severity and related mortality remains essential." (PMID 39272717, 2024). "Various studies also indicated that the serum levels of CRP and NLR and the pulmonary involvement level in CT scans were correlated with the severity of COVID-19 and the patients’ prognosis." (PMID 38395855, 2024). "However, neither CRP nor PCT was associated with poor outcomes in diabetic patients with COVID-19." (PMID 38455656, 2024). "Several studies report RNLS association with markers of inflammation but without consistency, that is, while being positively correlated with CRP in peritoneal dialysis patients, it was negatively correlated with ferritin, WBC, and IL-1 values in COVID-19." (PMID 39728688, 2024). "Although the D-dimer, Ferritin, CRP, ALT levels of COVID-19 patients with lung involvement with the AA genotype were high, it was not statistically significant (P > 0.05)." (PMID 39309472, 2024). "The severity of COVID-19 was an independent predictor of mortality in our study after adjustment for age, gender, DM, prior or new AMI, CRP, Ferritin, Procalcitonin, and fibrinogen values." (PMID 39697349, 2024). "This study identifies age, CRP levels, ferritin levels, and SIRI as significant predictors of the need for advanced respiratory support in COVID-19 patients during the early months of the pandemic." (PMID 39149665, 2024).
COVID-19 (continued). "There is also a study showing the simultaneous increase in CRP and PCT and DNA damage in COVID-19 patients." (PMID 39408623, 2024). "Though the CRP and ferritin concentration is reflective of the measure (degree) of acute inflammatory response, however, lack of adequate information on the contribution of systemic inflammation in COVID-19 pathogenesis could be highlighted as future research avenues." (PMID 38610151, 2024). "The COVID-19 patients showed a decrease in glucose levels, creatinine, and CT LDL (p ≤ 0.01) and an increase in CRP (0.01) in comparison with the HSs." (PMID 39057070, 2024). "High levels of IL-6, and consequently, C-reactive protein (CRP), are found in post-acute sequelae of COVID-19 (PASQ), also called long COVID or post-COVID-19 syndrome." (PMID 38248262, 2024). "In our study, CRP (AUC was 0.781) and PCT (AUC was 0.768) showed better predictive efficacy for 28-day mortality in COVID-19 patients compared to NLR (AUC was 0.677)." (PMID 38671532, 2024). "C-reactive protein (CRP), procalcitonin (PCT), and hemogram-derived ratios have been studied in several infectious diseases, such as sepsis and Coronavirus Disease-19 (COVID-19)." (PMID 39200069, 2024). "In summary, the findings showed that the prognosis of patients with severe COVID-19 was significantly correlated with inflammatory indicators such as WBC counts and CRP." (PMID 39469325, 2024). "It is also worth noting that despite CRP normalization and symptom resolution of the participants, both the VCO and control groups still had COVID-19-positive participants." (PMID 38282651, 2024). "A clinical study conducted in 2020 showed that virgin coconut oil (VCO) has been found effective in the rapid relief of COVID-19 symptoms and normalization of the C-reactive protein (CRP) concentration among probable and suspected cases of COVID-19." (PMID 38282651, 2024). "We calculated the sensitivity and specificity of CRP and IL6, using the established laboratory reference ranges or cut-off values, to predict hospitalization and severe COVID-19, respectively, in our study cohort." (PMID 39664394, 2024). "The aim of the study was to assess the correlation of aldosterone, urea, creatinine, C-reactive protein (CRP), and procalcitonin (PCT) levels with 28 days of mortality in patients treated for COVID-19 in the intensive care unit." (PMID 38570550, 2024). "Similar responses were observed, with CRP, SAA, LBP, and A1AG increasing with infection, which compared favorably with previous COVID-19 publications." (PMID 38879593, 2024). "We found that the expression levels of inflammation-related proteins (CRP, SAA1, SAA2, and ORM1) were substantially elevated in the acute phase of COVID-19, consistent with the proteomic results." (PMID 38965561, 2024). "The most common laboratory abnormalities seen in hospitalized COVID-19 patients include lymphocytopenia accompanied by an elevated neutrophil count, thrombocytopenia, anemia, raised LDH levels, D-dimer, CRP, liver enzymes, and decreased albumin levels." (PMID 37712883, 2024). "According to the cut-off points of CRP in ROC analysis, the prevalence of DKA or HHS in diabetics with COVID-19 were 3.7% vs 31.25% (P<0.05)." (PMID 38455656, 2024). "Inflammatory markers, namely CRP, IL-6, LDH, and Ferritin, exhibited a significant elevation in COVID-19 cases as compared to the control group." (PMID 38464514, 2024). "In the group of patients with COVID-19 in the ICU, the biomarkers ferritin, hepcidin, and C-reactive protein have higher values in the lower altitude region." (PMID 39062181, 2024). "Several inflammatory markers, such as C-reactive protein (CRP), interleukin-6 (IL-6), neutrophil-to-lymphocyte ratio (NLR), and ferritin, have been identified as predictors of COVID-19 severity." (PMID 39767616, 2024). "One study showed that IL-6 ≥ 74.98 pg/mL, CRP ≥ 81 mg/L, PCT ≥ 0.56 ng/mL, and d-dimer ≥ 760 ng/mL effectively predicted the in-hospital mortality in COVID-19 patients." (PMID 38104038, 2024).